ADD3 (adducin 3)
Description:
Membrane-cytoskeleton-associated protein that promotes the assembly of the spectrin-actin network. Plays a role in actin filament capping. Binds to calmodulin (Probable). Involved in myogenic reactivity of the renal afferent arteriole (Af-art), renal interlobular arteries and middle cerebral artery (MCA) to increased perfusion pressure. Involved in regulation of potassium channels in the vascular smooth muscle cells (VSMCs) of the Af-art and MCA ex vivo. Involved in regulation of glomerular capillary pressure, glomerular filtration rate (GFR) and glomerular nephrin expression in response to hypertension. Involved in renal blood flow (RBF) autoregulation. Plays a role in podocyte structure and function. Regulates globular monomer actin (G-actin) and filamentous polymer actin (F-actin) ratios in the primary podocytes affecting actin cytoskeleton organization. Regulates expression of synaptopodin, RhoA, Rac1 and CDC42 in the renal cortex and the primary podocytes. Regulates expression of nephrin in the glomeruli and in the primary podocytes, expression of nephrin and podocinin in the renal cortex, and expression of focal adhesion proteins integrin alpha-3 and integrin beta-1 in the glomeruli. Involved in cell migration and cell adhesion of podocytes, and in podocyte foot process effacement. Regulates expression of profibrotics markers MMP2, MMP9, TGF beta-1, tubular tight junction protein E-cadherin, and mesenchymal markers vimentin and alpha-SMA (By similarity). Promotes the growth of neurites (By similarity).
Synonyms: ADDL; CPSQ3
Tractability: Antibody: its Gene Ontology location is reachable by antibodies, with high confidence; UniProt places it where antibodies can reach, with medium confidence; the Human Protein Atlas places it where antibodies can reach. PROTAC: UniProt records ubiquitination sites on it; ubiquitination databases record sites on it; its protein half-life has been measured.
Gene: Protein-coding gene on chromosome 10 (109,996,356 to 110,135,565, forward strand). Ensembl gene ENSG00000148700.
Subcellular location: Cytoplasm, cytoskeleton; Cell membrane; Cytoplasm
Subcellular location (Human Protein Atlas): Plasma membrane
Pathways (Reactome):
Signal Transduction: RHOD GTPase cycle; RHOF GTPase cycle
Transport of small molecules: Miscellaneous transport and binding events
Gene Ontology:
Molecular function: actin filament binding; structural constituent of cytoskeleton
Biological process: barbed-end actin filament capping; regulation of actin filament polymerization; cytoskeleton organization
Cellular component: plasma membrane; cytoplasm; cytoskeleton; cytosol; membrane; postsynaptic density; spectrin-associated cytoskeleton; brush border; cell cortex; cell-cell junction; condensed nuclear chromosome
Genetic constraint (gnomAD): Loss-of-function variants: 18 observed, 67.56 expected, observed/expected ratio (o/e) 0.27, 90% interval 0.18 to 0.4. The upper end of that interval is the gene's LOEUF score, 0.4, which puts it in group 1 of 6, group 1 being the genes least tolerant of losing a copy. Missense variants: 708 observed, 784.28 expected, observed/expected ratio (o/e) 0.9, 90% interval 0.85 to 0.96. Synonymous variants: 258 observed, 268.99 expected, observed/expected ratio (o/e) 0.96, 90% interval 0.87 to 1.06.
Gene-disease validity (ClinGen):
ClinGen rates the evidence that ADD3 causes each of these diseases.
complex neurodevelopmental disorder with motor features (autosomal recessive): Moderate. A complex neurodevelopmental disorder that involves more than one phenotype associated with the central nervous system, including but not limited to intellectual disability, autism, and seizures (epilepsy).
Homologues: Orthologues: chimpanzee ADD3 (99% identical), macaque ADD3 (98% identical), dog ADD3 (97% identical), pig ADD3 (96% identical), guinea pig ADD3 (94% identical), rat Add3 (93% identical), mouse Add3 (92% identical), rabbit ADD3 (91% identical), zebrafish add3a (67% identical), tropical clawed frog add3 (65% identical), zebrafish add3b (53% identical), Drosophila melanogaster hts (37% identical), and 1 more. Paralogues in human: ADD2 (55% identical), ADD1 (52% identical).
Diseases named in the same sentence as ADD3 in open-access papers:
ADD3 is named in the same sentence as 46 diseases in open-access papers, as found by Europe PMC text mining. Sharing a sentence is not in itself a finding about the gene and the disease. The quoted sentences say what the papers report.
biliary atresia (9 papers, 2014 to 2025). A rare, biliary tract disease characterized by progressive obliterative cholangiopathy of the intra- and extrahepatic bile ducts, occurring in the embryonic/ perinatal period, leading to severe and persistent neonatal jaundice and acholic stool. "ADD3 encodes cytoskeleton protein and is generally regarded as an anti-oncogene, associated with biliary atresia." (PMID 37605290, 2023). "ADD3 is a gene, located in the 10q24.2 region, which has been indicated as a susceptibility gene for biliary atresia." (PMID 35204421, 2022). "Similarly, the rs564185858 (G367D) mutation in ADD3 has been linked to neurodevelopmental disorders, including cerebral palsy and schizophrenia, while additional ADD3 variants have been associated with biliary atresia and liver fibrosis." (PMID 40869965, 2025). "Based on the results of previous studies, the ADD3 gene, located in the 10q24.2 region, may be a susceptibility gene of biliary atresia (BA)." (PMID 25285724, 2014). "Other genes including FOXA2, GPC1, ADD3, PKD1L, EFEMP1/3, STIP1 were found to be associated with biliary atresia." (PMID 37324459, 2023). "Other studies have demonstrated that mutations in FOXA2, GPC1, ADD3, PKD1L1, EFEMP1/3, STIP1, XPNPEP1, REV1 and JAG1 genes can increase an individual’s genetic susceptibility to biliary atresia." (PMID 37324459, 2023).
glioblastoma (9 papers, 2017 to 2025). The most malignant astrocytic tumor (WHO grade IV). "The angiogenesis-promoting effect of CM derived from ADD3-silenced ASCs was consistent with the effect of CM from ADD3-deficient glioblastoma multiforme cells, reported by Kiang." (PMID 37605290, 2023). "Morphoregulatory ADD3 controls glioblastoma stem cell (GSC) connectivity, proliferation, and chemoresistance, showing that GSC morphology is a new layer of tumor heterogeneity." (PMID 39592188, 2025). "Their study demonstrated that miR-145 acted as a tumor-suppressor in glioblastoma since it apparently reduced proliferation, adhesion and invasion of glioblastoma cells, apparently by suppressing the activity of ADD3 and oncogenic protein Sox9." (PMID 28476036, 2017). "A recent study revealed that miR-145 may suppress the activity of ADD3 and inhibit the proliferation of glioblastoma cells." (PMID 32373210, 2020). "In this study, we unveil how the assessment of ADD3 deletion provides clinical significance in glioblastoma (GBM)." (PMID 34970477, 2021). "For example, miR-216b inhibited the proliferation and invasion of non-small cell lung cancer (NSCLC) cells by directly targeting SOX9, and miR-145 reduced the adhesion and invasion of glioblastoma cells by inhibiting the carcinogenic proteins of SOX9 and ADD3." (PMID 37328795, 2023). "ADD3 has been identified as a novel tumor suppressor located on chromosome arm 10q, and it may link LOH on chromosome 10q to glioblastoma development and progression." (PMID 40277764, 2025). "Another in vitro study described an increase in ADD3 expression in temozolomide resistant glioblastoma cells and that its expression is colocalized with CD133 in glioma stem-like cells, suggestive of a positive correlation between ADD3 and cancer stem cell phenotype as well as chemoresistance." (PMID 29862265, 2018).
glioma (8 papers, 2006 to 2025). A benign or malignant brain and spinal cord tumor that arises from glial cells (astrocytes, oligodendrocytes, ependymal cells). "Downregulation of ADD3 expression was associated with increased migratory activity of human glioma cells in vitro, and decreased expression of ADD3 has been described in astrocytomas." (PMID 17002787, 2006). "The fact that ADD3 is dysregulated at the genetic level should be further explored in regard to the underlying mechanisms of tumor progression and genetic vulnerabilities in glioma." (PMID 34970477, 2021). "Furthermore, we showed progressive loss of ADD3 in six out of seven patient-paired gliomas with malignant progression, as well as in recurrent GBMs." (PMID 34970477, 2021). "Among these putative tumor suppressor genes, ADD3 was found to be downregulated in high-grade gliomas when compared with its less malignant counterpart in several gene expression profiling studies." (PMID 34970477, 2021). "ADD3 protein expression was determined by Western blotting and IHC in another cohort with 10 patient-paired primary–recurrent gliomas (P1–10)." (PMID 34970477, 2021). "In this study, we were able to demonstrate the mechanism by which ADD3 was downregulated in gliomas as being most likely due to LOH with copy number deletions." (PMID 34970477, 2021). "While the tumor-suppressive role of MXI1 in glioma has been reported, less is known about the role of ADD3 in glioma." (PMID 34970477, 2021). "Whereas genetic loci with allelic deletion often implicate tumor suppressor genes, a putative tumor suppressor Adducin3 (ADD3) mapped to chromosome 10q25.2 was found to be preferentially downregulated in high-grade gliomas compared with low-grade lesions." (PMID 34970477, 2021). "In this study, we showed that LOH at D10S173 (ADD3/MXI1) was frequently seen in high-grade gliomas compared with low-grade gliomas and with a high proliferative index, and the results were suggestive of the role of these genes in regulating tumor progression." (PMID 34970477, 2021). "Another microarray analysis also found a reduced ADD3 expression in relation to increased migratory activity in glioma cells." (PMID 29862265, 2018). "The most frequently lost and underexpressed genes mapped at 10q and involved candidate genes in gliomas such as ADD3, between others." (PMID 17002787, 2006). "ADD3 is significantly downregulated in gliomas, demonstrating that its downregulation may promote tumour malignancy progress." (PMID 38520221, 2024). "ADD3 plays a tumour inhibitory role in regulating glioma growth and angiogenesis." (PMID 37952042, 2023). "In line with our hypothesis, further losses of ADD3 protein expression were observed in 6 out of 7 gliomas progressing to a higher malignancy grade (P1–P7)." (PMID 34970477, 2021). "Moreover, the growth suppressive effect of forced miR-145 overexpression in glioma cells is likely to be mediated through the suppression of Sox9 and ADD3 proteins." (PMID 29862265, 2018). "Furthermore, ADD3 has been associated with temozolomide (TMZ) resistance, glioma progression, and reduced glioma cell motility." (PMID 39592188, 2025). "However, LOH events at only the ADD3/MXI1 locus provided prognostic significance with a marked reduction in patient survival and appeared to have diagnostic potential in differentiating high-grade gliomas from low-grade ones." (PMID 34970477, 2021). "Then, through LASSO regression, 5 genes (ADD3, GRHPR, KLF13, RHBDL1 and SLC9A9) closely related to the prognosis of WHO Grade 4 glioma patients were selected." (PMID 37952042, 2023). "Furthermore, increased expression of ADD3, another member of the adducin family, in TMZ-resistant GBM cells and in glioma stem-like cells has previously been reported, implying a potential positive association between adducin and the CSC phenotype." (PMID 38253025, 2023).
glioma (continued). "That said, microarray gene expression profiling studies have found that ADD3 mRNA expression was in fact significantly downregulated during glioma progression when compared to its less malignant or nonneoplastic counterparts." (PMID 29862265, 2018).
Hypertension (6 papers, 2015 to 2025). The presence of chronic increased pressure in the systemic arterial system. "Mutations in the genes ADD1, ADD2, and ADD3 have been linked to hypertension, neurodevelopmental disorders, and cancer." (PMID 40869965, 2025). "Variants in ADD3 were found to be associated with hypertension, cerebral palsy, renal disease, vascular disease and cognitive dysfunction." (PMID 37886469, 2023). "However, it was shown that in FHH K572Q rats, the ADD3 gene contributes to modifying the myogenic response and the autoregulation of renal and cerebral blood flow, which results in increased susceptibility to kidney disease caused by hypertension." (PMID 40722594, 2025). "We also investigated adducin, the heterodimeric cytoskeleton protein whose three subunits are encoded by ADD1, ADD2 (protein accession number C9J080, FC = 0.00), and ADD3, respectively; the role of adducin in hypertension and its downregulation-related disorders have been reported." (PMID 36002804, 2022). "The heart proteins ADD3, PTGIS, and COL1A2 are candidates for hypertension and myocardial infarction." (PMID 35259090, 2022).
cerebral palsy (5 papers, 2017 to 2025). A group of disorders affecting the development of movement and posture, often accompanied by disturbances of sensation, perception, cognition, and behavior. "Recently, a homozygous mutation in ADD3 was shown to cause cerebral palsy, epilepsy, borderline microcephaly, thin corpus callosum and intellectual disability in one family." (PMID 29768408, 2018). "Notably, ADD3, alternatively known as Adducin 3, is a protein-coding gene involved in disorders including cerebral palsy, spastic quadriplegic 3, and spastic quadriplegic cerebral palsy." (PMID 41593936, 2025).
lung carcinoma (5 papers, 2012 to 2025). "Given that the cytoskeleton structures are essential for cell motility, downregulation of ADD3 has been shown to be associated with enhanced migratory and invasive potential in lung cancer cells." (PMID 34970477, 2021). "Other interesting targets for AS regulation by QKI in lung cancer are ESYT2 and ADD3, which encode proteins involved in cytoskeleton organization." (PMID 34065983, 2021). "Even in the previous lung cancer study, there was also heterogeneous evidence for alternative splicing patterns of ADD3 (four of 18 lung-cancer patients showed a cassette exon exclusion for ADD3)." (PMID 22905095, 2012). "Although this screening method has its limitations, it could be a useful strategy to discover drugs that counteract dysregulated mRNA splicing patterns in lung cancer, using a similar construct with a NSCLC-specific cassette exon, such as e.g., from the NUMB, ADD3, or caspase-9 genes." (PMID 34065983, 2021).
non-small cell lung carcinoma (5 papers, 2012 to 2020). A group of at least three distinct histological types of lung cancer, including non-small cell squamous cell carcinoma, adenocarcinoma, and large cell carcinoma. "Other cancer that shows EGFR amplification, such as non-small cell lung cancer, shares this ADD3 infraexpression associated with cell migration." (PMID 33172155, 2020). "In a recent study using exon array, transcript variants of ADD3 have been further validated and found to be differentially spliced between non-small-cell lung cancer (NSCLC) and normal lung tissue." (PMID 29862265, 2018). "The differential splicing of ADD3 has been found in the non-small cell lung cancer and the murine breast tumor." (PMID 22905095, 2012). "ADD3 is a subunit of adducins 52 and its alternative splicing events have been reported in HER2-positive breast cancer 53 and in non-small cell lung cancer." (PMID 32373210, 2020). "The AS events in MAFC1, ADD3 and NUMB were reported in the two recent researches in non-small cell lung cancer." (PMID 24622401, 2014). "In addition, ADD3 alternative splicing events have been reported in HER2-positive breast cancer 53 and in non-small cell lung cancer." (PMID 32373210, 2020).
breast carcinoma (3 papers, 2020 to 2021). "To further confirm the presence of IDR in the protein regions encoded by breast-cancer-associated AS events, we analyzed ADD3, PACSIN2, DIAPH1, MARK3, and MAP3K7 protein sequences with the PONDR web tool, a predictor of natural disordered regions." (PMID 34202984, 2021). "Collectively, these results suggest that CDYL2a promotes breast cancer cell proliferation through, at least partly, regulating the alternative splicing of FIP1L1, NKTR, and ADD3 genes." (PMID 32373210, 2020). "Finally, in our functional analysis of aberrantly expressed AS exons in breast cancer cells and tissues (PACSIN2 exon 8, DIAPH1 exon 2, MARK3 exon 16, ADD3 exon 13, and MAP3K7 exon 12), we found that dysregulated cassette exons encode for IDRs." (PMID 34202984, 2021). "Importantly, we were also able to confirm, by RT-PCR, the aberrant AS regulation of PACSIN2, DIAPH1, MARK3, ADD3, MAP3K7, and MARK2 in RNA extracts from two human tumor breast cancer samples tissues and two non-pathological tissues." (PMID 34202984, 2021).
breast tumor (3 papers, 2012 to 2021). "Interestingly, among validated AS events that are highly dysregulated in cancer cells, we found ADD3 exon 13, an exon previously identified as being up-regulated in highly metastatic murine breast tumors." (PMID 34202984, 2021). "Future studies may target ADD3 depleted tumors as a novel therapeutic approach utilizing synthetic lethality, which can be developed to target gene defects in tumors with ADD3 deletion, similar to the concept of using PARP inhibitors exclusively for BRCA-mutated breast tumors." (PMID 34970477, 2021).
Intellectual disability (3 papers, 2013 to 2022). "Here, we report the pathogenicity of ADD3 mutations in three families with intellectual disability, microcephaly, cataracts and skeletal defects." (PMID 29768408, 2018). "Here, we identified three families with mutations in ADD3, encoding for adducin-γ, with intellectual disability, microcephaly, cataracts and skeletal defects." (PMID 29768408, 2018). "In this study, we identify three families with mutations in ADD3, encoding for adducin-γ, with intellectual disability, microcephaly, cataracts and skeletal defects, further supporting that ADD3 is a disease gene as previously reported for a single family." (PMID 29768408, 2018). "In summary, we have identified a homozygous p.G367D mutation in ADD3 in children with spastic diplegic/quadriplegic CP and intellectual disability." (PMID 23836506, 2013).
liver fibrosis (3 papers, 2017 to 2025). "In addition, upregulated expression of ADD3 is also reported to contribute in liver fibrosis in BA and associated with downregulation of miR-145 which targets ADD3." (PMID 29862265, 2018). "As both ADD3 and p-Akt were regulated by miR-145-5p in LX-2 cells, we suppose that ADD3 may play a role in Akt signaling pathway, and facilitate the activation and proliferation of LX-2 cells, and thus contributes to advanced liver fibrosis." (PMID 28902846, 2017). "Downregulated miR-145-5p may contribute to liver fibrosis in BA by up-regulating the endogenous expression of ADD3." (PMID 28902846, 2017). "The downregulation of miR-145 may contribute to liver fibrosis in BA by upregulating the expression of ADD3." (PMID 28902846, 2017).